CTLA4 (cytotoxic T-lymphocyte associated protein 4)
Diseases named in the same sentence as CTLA4 in open-access papers (continued):
Sharing a sentence is not in itself a finding about the gene and the disease.
tumor (continued). "Acting in concert with a costimulatory CTLA-4 checkpoint inhibitor, Id2kd-N2a whole tumor cell vaccination generated a potent tumor-specific T-cell response, capable of eradicating established tumors in 60% of mice." (PMID 29377881, 2018). "CTLA-4 blockade with ipilimumab should lead to suppression of Treg function, allowing an immune response to tumor antigens to emerge and expand." (PMID 29973204, 2018). "Recently, anti-tumor effect can be obtained by suppressing its function by using monoclonal antibody against CTLA-4, PD-1 or PD-L1, thereby, enhancing the tumor-specific T cell activity and effect." (PMID 30680248, 2018). "Nevertheless, anti-CTLA-4 and anti-PD-1 have demonstrated a powerful anti-tumor response by activating the immune system." (PMID 30486519, 2018). "Although CTLA-4 impinges on many features of T-cell biology, its effect on tissue and tumor infiltration will be the subject of exciting future work." (PMID 30542345, 2018). "In this study, the presence of extracranial tumor was necessary for effective responses by combined anti-CTLA-4 and anti-PD-1 therapy." (PMID 30301252, 2018). "Inhibition of CTLA-4 induced the upregulation of PD-L1, as well as the activation of the EGFR pathway in NSCLC cells, highlighting a distinct function of CTLA-4 in tumor cells compared to T cells." (PMID 30577587, 2018). "Co-inhibiting the expressions of PD-1 and CTLA-4 can effectively suppress the growth of H22 hepatoma and promote the apoptosis of tumor cells in mice." (PMID 30564277, 2018). "Therapeutic potential of a systemically delivered VSV encoding tumor antigens c-Myc, HIF-2α, and Sox-10 in combination with anti-PD-1 or anti-CTLA-4 therapy has been shown in a pre-clinical glioma model." (PMID 29857493, 2018). "In this model, a combined treatment of the tumor-bearing mice with anti-PD1 and anti-CTLA4 antibodies also limits the tumor outgrowth by ~50% compared with a vehicle treatment." (PMID 29670880, 2018). "The therapeutic benefits of CTLA-4 antibody blockade were identified in murine tumor models, but the potential for PD-1 or PD-L1 blockade as a novel CI therapy arose from observational studies in humans." (PMID 30319637, 2018). "CTLA-4 and PD-1 pathways are currently targeted to enhance anti-tumor responses in melanoma patients and individuals suffering from various other cancers." (PMID 30201974, 2018). "Inhibition of both CTLA-4 and the PD-1/PD-L1 axis has demonstrated clinical benefit in several tumor types." (PMID 29721177, 2018). "Analysis of the phenotypical and functional evolution of CD8+ TILs from 32 patients with NSCLC revealed that the accumulative expression of PD-1, TIM3, CTLA-4, LAG-3, and BTLA on CD8+ T cells was associated with tumor stage and nodal status." (PMID 29482595, 2018). "When the vaccine was combined with both CTLA-4 and PD-L1 inhibition, all mice (n = 16 in both studies) were cured of their tumors and remained tumor free for 6 months in follow-up (log-rank test for survival, p = 0.0006)." (PMID 29377881, 2018). "By binding with its ligand B7 molecules, CTLA-4 produces inhibitory signals and inhibits the activation of T cells to protect the tumor cell from attack." (PMID 30564277, 2018). "This triple combination therapy includes external beam radiation to the tumor, intratumoral injection of a tumor-specific immunocytokine (anti-GD2 mAb linked to IL2) and anti-CTLA-4." (PMID 30400822, 2018). "Combining PD-L1 checkpoint inhibition with whole tumor cell/anti-CTLA-4 vaccination enhanced tumor cell killing, cured mice with established tumors, and induced long-term immune memory (6 months)." (PMID 29377881, 2018). "An existing study shows that inhibiting the binding of CTLA-4 and its ligands also can downregulate Bcl-2 and promote the apoptosis of tumor cells." (PMID 30564277, 2018). "Infiltration of pmel-1 T-cells into the tumor was seen in the anti-PD-1, CTLA-4, and 4-1BB monotherapy groups, but the degree of infiltration was similar to the controls." (PMID 29348598, 2018).
tumor (continued). "Dexamethasone exposure reduced the total number of T cells in the majority of T cell subsets along the differentiation spectrum in the tumor-draining lymph nodes, yet as observed in vitro, this was partially rescued by CTLA-4 blockade." (PMID 29891009, 2018). "The introduction of Bacteroides fragilis to germ-free mice restored their ability to respond to anti-CTLA-4 antibodies by increasing T-cell responses close to the tumor site." (PMID 31294239, 2018). "One of the most successful approaches to mount CD8+ T cell-mediated anti-tumor immune reaction is the administration of checkpoint inhibitors, i.e., blocking antibodies against inhibitory checkpoint receptors (e.g., PD-1 and CTLA4) or ligands (e.g., PD-L1)." (PMID 29670880, 2018). "While tumor expression of PD-L1 has been shown to have objective responses to anti-PD-L1 immunotherapies, the clinical implications of CTLA-4 expression in tumor cells or immune cells in the tumor microenvironment is still controversial." (PMID 29672601, 2018). "Our models suggest that whole tumor cell vaccination with Id2kd cells plus anti-CTLA-4 induces the appropriate T-cell response needed." (PMID 29377881, 2018). "Patients with high expression levels of immune-related genes in tumor biopsies prior treatment were more likely to respond to CTLA-4 blockade." (PMID 29494517, 2018). "Host immunity recognizes and eliminates most early tumor cells, yet immunological checkpoints, exemplified by CTLA-4, PD-1, and PD-L1, pose a significant obstacle to effective antitumor immune responses." (PMID 30191140, 2018). "Over the past few years, the tumor microenvironment has been intensively investigated, with a focus on the tumor and the host immune response, particularly from the perspective of immune checkpoint molecules, including PD-L1, PD-1 and CTLA-4." (PMID 29732001, 2018). "This strengthens the notion that tumor-specific T-cell populations are affected by CTLA-4 or PD-1 inhibition." (PMID 29896449, 2018). "Further, inhibition of Jab1/COPS5 cooperates with anti-CTLA4 to enhance anti-tumor T cell function and decrease tumor growth." (PMID 29535627, 2018). "Apart from PD-1 and CTLA-4, there are several other checkpoint proteins in tumor microenvironment that play a role in dampening the anti-tumor immune response." (PMID 30400822, 2018). "LAG-3 regulates anti-tumor immune responses interestingly parallels to CTLA-4, a well-known cancer immune checkpoint." (PMID 30603054, 2018). "A conspicuous inhibition on MC-C tumor was observed when an anti-CTLA-4 treatment was initiated at early stages of tumor growth; however, as tumor grew, tumor-stimulatory effects were observed." (PMID 29435437, 2018). "Consistent with its superior antitumor efficacy, treatment of A375-tumor-bearing mice with a-CTLA4-TGFβRII resulted in a greater elevation in tumor-reactive IFN-γ-expressing CD8+ cells compared with treatment with a-CTLA-4." (PMID 29467463, 2018). "The CTLA-4 antibody mediates anti-tumour immunity through Akt phosphorylation and the blockade of Foxp3+ Treg cells in the TME, which allows for potent T-cell expansion." (PMID 29848327, 2018). "This study demonstrates that the activity of anti-CTLA-4 antibodies depends, at least in part, on the depletion of tumor-infiltrating regulatory T (Treg) cells in the context of human FcγRs and human IgGs." (PMID 29576375, 2018). "Whereas CTLA-4 is highly expressed on Tregs, PD-L1 is overexpressed on tumor cells as well as tumor-infiltrating T cells, where it cooperates with TGFβ to inhibit T-cell activation and induce and maintain Tregs70." (PMID 29467463, 2018). "Several groups have established that anti-mouse CTLA-4 antibodies induced tumor rejection through selective depletion of regulatory T (Treg) cells in the tumor microenvironment." (PMID 29713453, 2018).
tumor (continued). "Most recently, novel immunotherapies, in particular checkpoint inhibition with anti-CTLA-4 and anti-PD-1/-PD-1L antibodies targeting negative regulatory receptors on T cells, have been successfully applied against a growing number of tumor types." (PMID 29794999, 2018). "This is in part due to the upregulation of several inhibitory receptors like PD-1, LAG3, TIGIT, and CTLA-4 that desensitize T cells to tumor antigens." (PMID 29482595, 2018). "Several clinical trials are underway with ipilimumab and a human IgG2 anti-CTLA-4 antibody, tremelimumab, alone and in combination with other immunomodulatory antibodies, tumor-targeting antibodies, small molecule therapies and therapeutic cancer vaccines." (PMID 29617360, 2018). "In some manner, this combination of anti-CTLA-4 effects on motility combined with stabilization as mediated by NKG2D enhanced tumor eradication." (PMID 30542345, 2018). "Further studies are also required to define the prognostic role of neutrophils, CTLA-4 expression in tumor cells and PD-L1 expression in immune cells." (PMID 29872507, 2018). "After the discovery of CTLA-4's immunosuppressive function, antibody-mediated CTLA-4 blockade caused tumor regression in murine models." (PMID 30568917, 2018). "Based on these data and other recent publications on the subject, we propose that anti-human CTLA-4 antibodies induce tumor rejection by selective depletion of Tregs in the tumors rather than blockade of B7-CTLA-4 interaction in lymphoid organs." (PMID 29713453, 2018). "Nevertheless, in animal models, activation of co-stimulatory receptors such as OX40 and blockade of co-inhibitory receptors such as PD1 and CTLA4 induced tumor regression and increased long-term survival." (PMID 29692957, 2018). "Antigen specific activation of naïve T cells induces the expression of cytokines such as interferon-γ, which in turn triggers CTLA-4 expression in surrounding immune and tumor cells." (PMID 29682176, 2018). "Curcumin enhanced the therapeutic efficacy of anti-CTLA4 in mice, leading to decreased tumor growth and enhanced survival." (PMID 29535627, 2018). "In an early preclinical study, CTLA-4 blockade delayed B16 tumor growth when combined with a GM-CSF-secreting tumor vaccine, showing the value of combination immunotherapy." (PMID 29623082, 2018). "Binding of CTLA-4 and PD-1/PD-L1 to cancer cell or tumor-microenvironmental ligands leads to T cell attenuation, which enables the tumor cells to avoid immune-mediated destruction." (PMID 29544515, 2018). "A combination of anti-SEMA4D Ab with CTLA-4 Ab had a synergistic effect in complete tumor rejection, was more effective in tumor inhibition than anti-CTLA-4 Ab and anti-PD-1 Ab combination, and more significantly prolonged survival." (PMID 30134791, 2018). "Further studies investigated the effects of anti-CTLA-4 therapy on the frequency and phenotype of tumor-infiltrating or blood-circulating T cells." (PMID 29494517, 2018). "The first generation of immune checkpoint inhibitors (anti-CTLA-4 and anti-PD-1/PD-L1) targeted natural immune homeostasis pathways to drive anti-tumor immune responses." (PMID 30450335, 2018). "Immune suppression in the tumor microenvironment through PD-1 or CTLA-4 occurs in various tumors, and immune checkpoint inhibitors (anti-PD-1, anti-PD-L1, or anti-CTLA-4) amplify antitumor T-cell response." (PMID 29662490, 2018). "It has been reported that in the breast TME, both malignant mammary epithelial cells and tumor-infiltrating lymphocytes (TILs) express multiple immune checkpoints/ligands, including PD-1, CTLA-4, and PD-L1 to support immune evasion." (PMID 29983831, 2018). "Preclinical studies in mice have shown that optimal anti-tumor activity of anti-CTLA-4 antagonist antibodies required co-engagement of FcγRs expressed by tumor-associated effector cells." (PMID 29617360, 2018).
tumor (continued). "The results of quantitative RT-PCR showed that the mRNAs for PD-1 and CTLA-4 were downregulated in spleen tissue in the three siRNA groups, while the PD-L1 mRNA and protein levels increased significantly in the tumor, but decreased in the liver." (PMID 30564277, 2018). "Immunostimulatory therapies targeting co-inhibitory T-cell checkpoint pathways such as PD-1 and CTLA-4 produce lasting anti-tumor responses in a proportion of patients with diverse malignancies, including NSCLC." (PMID 30400835, 2018). "We previously reported that tumor vaccination plus anti-CTLA-4 antibody was surprisingly more effective in an aggressive mouse cell line (AgN2a) (90% cure) than in the wild-type Neuro2a cell line (60% cure)." (PMID 29377881, 2018). "In murine breast cancer models, CTLA4 blockade using specific antibodies increased the motility of tumor infiltrating lymphocytes (TILs) in the tumor cavity in vivo." (PMID 30542345, 2018). "The induction of markers of immunogenic cell death can predict the ability of drugs to induce anti-tumor immunity, and these types of drugs would be good candidates for the potential synergy with anti-CTLA-4." (PMID 30441807, 2018). "Treg cell reduction has been identified as a major anti-tumor activity of anti-CTLA-4 antibodies in preclinical models." (PMID 28920002, 2017). "In conclusion, HDAC inhibition increases PD-L1 and HLA-DR expression in TNBC and decreases Treg frequency, which when combined with PD-1 and CTLA-4 blockade promotes TILs infiltration, tumor apoptosis, tumor regression and increased survival in mice." (PMID 29371976, 2017). "If validated in larger, confirmatory studies, tumor cell CTLA-4 expression in LN+ is a promising prognostic marker, readily available in surgically treated patients." (PMID 28707078, 2017). "In NSCLC, low levels of immunotherapy biomarkers correlate with a poor anti-tumor response to anti-PD-1 and anti-CTLA4 inhibitory antibodies." (PMID 29163826, 2017). "In our large, unselected NSCLC patient cohort, we demonstrate that high expression of CTLA-4 on tumor epithelial cells in regional LN+ independently predicts poor DSS." (PMID 28707078, 2017). "Lycorine hydrochloride and anti-CTLA-4 synergistically decreased tumor weight, lung metastasis, and luciferin-staining in tumor images." (PMID 28416753, 2017). "By blocking CTLA-4 and/or PD-1 signaling in T cells, cellular immune responses are unleashed with remarkable effects on tumor regression and long-term ‘cure’ can be achieved (reviewed in ref.45)." (PMID 29176694, 2017). "To examine the changes occurring with the combination therapy on both local and systemic level, we analysed the effect of NDV-ICOSL and CTLA-4 blockade on the TILs from the treated tumours and on the splenic T-cell populations." (PMID 28194010, 2017). "For example, in the context of tumours, exhausted T cells express a whole set of inhibitory receptors with likely irredundant functions, such as CTLA4, TIM3, LAG3, TIGIT and others." (PMID 28537896, 2017). "Because of the fact that CTLA-4 and PD-1 play a crucial regulatory role in tumor immunoreaction process, their inhibitors have been well studied for a long period and demonstrated exciting benefit in clinical cancer therapy." (PMID 28536525, 2017). "Immune checkpoint molecules including CTLA-4, PD-1 and PD-L1 are key molecules involved in maturation and suppressive functions of tumor-infiltrating T cells." (PMID 28574843, 2017). "By simultaneously blocking CTLA-4 and PD-1, clinical anti-tumor response should improve, as their inhibitory signals will be blocked at multiple steps and in multiple cell types." (PMID 29211042, 2017). "Predictive biomarkers based on tumor-intrinsic factors or the tumor microenvironment have been investigated for both CTLA-4 and PD1 ICI." (PMID 29034210, 2017). "Staining intensity for CTLA-4 in tumor epithelial cells (T-CTLA-4) was relatively homogenous within each tumor, with variable intensity between tumors." (PMID 28707078, 2017).
tumor (continued). "Next, we studied the phenotypes of neoantigen-specific T cells derived from tumour-bearing mice that underwent anti-CTLA-4 checkpoint blockade immunotherapy." (PMID 28916749, 2017). "This extensive temporal interval before achieving complete tumor response likely reflects the time necessary for T-cells to uncouple from CTLA-4 mediated inhibition, undergo activation, and subsequently infiltrate and eradicate the tumor." (PMID 29179523, 2017). "For example, the efficacy of anti-CTLA-4 treatment depends on the immunogenicity of the tumor and can be dramatically enhanced by co-administration of a GM-CSF vaccine." (PMID 28611299, 2017). "Specific antibodies blocking CTLA-4 function enhance T-cell stimulation and promote anti-tumor immunity." (PMID 28403812, 2017). "One patient had elevated frequencies of all three inhibitory receptors on CD8 T cells in the tumour but this represented only limited co-expression of PD-1, CTLA-4 and Tim-3." (PMID 28423034, 2017). "A study demonstrating in vitro induction of tumor cell apoptosis upon CTLA-4 engagement with B7 ligands supports a potential positive prognostic impact of T-CTLA-4." (PMID 28707078, 2017). "The expression of immune-related genes, also referred to as immune gene signature, of tumor tissues correlated to CTLA-4 ICI response in all four studies, two of which also found correlations to PFS or OS." (PMID 29034210, 2017). "Successful human trials of PD-1/CTLA-4 blocking antibodies have demonstrated the great potential of these agents in tumour immunotherapy." (PMID 28423034, 2017). "These antibodies target CTLA-4 or PD-1 molecules on T-cells, resulting in prolonged activation of T-cell responses, including potential tumor-reactive T-cell responses." (PMID 29034210, 2017). "We find that CD8 T cell infiltrates are prominent in the tumour tissue and that patients can express an elevated fraction of PD-1, CTLA-4 or Tim-3-expressing T cells." (PMID 28423034, 2017). "The triple combination also increased tumor-specific CD8 T cells systemically compared to ISF35 monotherapy or anti-CTLA-4 plus anti-PD-1 double therapy, supporting the role of tumor-specific CD8 T cells in both local and distant tumor suppression." (PMID 29129918, 2017). "Among many immune checkpoint proteins, programmed death 1 (PD-1) and CTLA4 are primarily employed by cancer cells to dampen anti-tumor immune response." (PMID 28536354, 2017). "Vorinostat, the immunotherapy combination (a-PD-1 + a-CTLA-4) and the three-drugs combination reduced the tumor burden by 12.5%, 34% and 88.5%, respectively." (PMID 29371976, 2017). "CTLA-4 blockade and imatinib synergize in mouse models to reduce tumor volume via intratumoral accumulation of CD8+ T cells." (PMID 28428884, 2017). "Targeting the immune checkpoint molecules CTLA-4, PD-1, and PD-L1 is revolutionizing clinical management for a variety of solid and hematological malignancies by generating durable anti-tumor immune responses." (PMID 29163490, 2017). "Transient exposure of tumors to AR42 or sodium valproate enhanced the anti-tumor efficacy of a subsequent anti-PD-1 antibody and of an anti-CTLA4 antibody." (PMID 29137331, 2017). "Phase 1 and 2 studies in multiple different tumor sites continue, mainly with CTLA-4 blockade (or other novel immune targets such as OX40) with radiotherapy." (PMID 28730140, 2017). "We tested this principle by treating mice bearing 2 tumors on the right and left flank with ISF35 only in the right flank tumor, followed by systemic anti-CTLA-4 and anti-PD-1 mAbs." (PMID 29129918, 2017). "This suggested that blocking of CTLA-4 in combination with trAb treatment enhances T-cell activation in a tumor-selective manner." (PMID 27966460, 2017). "Blocking inhibiting signals for T cells in order to enhance the anti-tumor effects has become a promising cancer therapy, and it has been implemented through CTLA-4 and B7-H1 blockade in early years." (PMID 28978159, 2017).